ENSG00000207022
Synonyms: LOC124900443
Gene: Small nucleolar RNA gene on chromosome 1 (92,846,059 to 92,846,182, forward strand). Ensembl gene ENSG00000207022.
Gene Ontology:
Biological process: RNA processing
Cellular component: nucleolus
Homologues: Paralogues in human: SNORA51 (88% identical).